ARG1 (arginase 1)
Diseases named in the same sentence as ARG1 in open-access papers (continued):
Sharing a sentence is not in itself a finding about the gene and the disease.
cancer (continued). "Moreover, the upregulation of VEGF and Arg1 in macrophages contributes to the development of cancer since tumor growth is supported by inducing neovascularization and by providing the substrates for cancer cell proliferation." (PMID 31737570, 2019). "It was reported that poor prognosis is linked to increased levels of CD163 (TAM marker with M2 phenotype), CSF-1 (colony-stimulating factor-1), major regulator of macrophage lineage, and Arginase-1 (Arg-1) – markers of TAM’s activity – in several cancers including the HPV-related ones." (PMID 29976244, 2018). "In cancer patients, ARG1 was expressed in both circulating and tumor-infiltrating MDSCs." (PMID 29921770, 2018). "Arg1 was significantly higher for cancer patients compared to the healthy volunteers." (PMID 29254508, 2017). "In addition, Arg1 protein and activity have been reported to be elevated in the plasma of cancer patients compared to healthy donors and we observed inhibition of arginase activity by CB-1158 in plasma isolated from cancer patients." (PMID 29254508, 2017). "Thus, pharmacological inhibition of Arg1 is a compelling therapeutic strategy for the treatment of cancer." (PMID 29254508, 2017). "Arg1 is upregulated in myeloid cells—including macrophages, neutrophils, and myeloid-derived suppressor cells—in response to various conditions, including infections, cancer, and pregnancy." (PMID 29201027, 2017). "Blocking Arg1 activity in the context of cancer could therefore shift the balance of L-arginine metabolism to favor lymphocyte proliferation." (PMID 29254508, 2017). "Subsequently, HIF-1α may create “pseudo-hypoxia” by enhancing the transcription of a series of hypoxia-related genes such as Arg-1, which can metabolize arginine to provide the substrates for cancer cell proliferation." (PMID 26474279, 2015). "Furthermore as arginase-1 has also been shown to have potent T cell modulatory effects MKP-2 influences are likely to have significant consequences for inflammatory disease and cancers where arginase-1 and iNOS have already been identified as key players." (PMID 23966857, 2013). "In a similar manner, ARG1 plays a pivotal role in tumorigenesis and metastasis, and it can be used as potential diagnosis biomarker for cancer progression, while the soluble form of IL12RB1 may truncate the capacity of the immune system to trigger a pro-inflammatory Th1/Th17 response." (PMID 40806007, 2025). "CD204+ TAM polarization and Cox2 and Arg1 expression levels in the THP-1 cells cultured with Cat D mutation cancer cells were dramatically decreased, whereas those of pY-STAT1 were increased relative to those of the THP-1 cells cultured with Cat D WT cancer cells." (PMID 38297161, 2024). "Importantly, however, it remains to be determined whether the differential expression of ARG1 between mice and humans poses any problem for the translation of this approach towards cancer patients." (PMID 39211039, 2024). "However, ARG1 had low expression in cancer tissues and high expression in normal tissues." (PMID 36733434, 2023). "In addition, when stimulating bone marrow-derived macrophages (BMDMs) with cancer cell conditioned medium, we detected significantly higher levels of the anti-inflammatory macrophage marker Arg1 when KPC cells expressed HAPLN1, indicating that HAPLN1 in ECM promotes TAM education." (PMID 37095087, 2023). "Additionally, sitravatinib inhibited expression of the M2 markers arginase 1, YM-1 and Fizz-1 upon stimulation with conditioned media from murine cancer cells – a source of TAM receptor ligands – and reduced immunosuppressive cell populations, such as MDSCs and M2 macrophages, in vivo." (PMID 35767205, 2022). "Moreover, we showed with immunofluorescence on mixed macrophages-cancer cells spheroids a decrease in the expression of Arginase 1 and CD206, both markers of the pro-tumoral phenotype, when they were cultivated in presence of the conditioned medium from Poly (I:C)-treated macrophages." (PMID 33402730, 2022).
cancer (continued). "Moreover, the immunofluorescence staining indicated that overexpression of NRBP2 in cancer cells significantly reduced the fluorescence intensity of Arg1 in the macrophages (oe-NC vs. oe-NRBP2: TPC-1: 49.31 vs. 18.42, p < 0.0001; CAL62: 42.16 vs. 13.76, p < 0.0001)." (PMID 35491849, 2022). "Next, we investigated whether an ODN containing consecutive guanosines affected the secretion of immune suppressive enzymes such as IDO and arginase 1 from cancer cells, as the latter is an important mechanism of resistance underlying immune checkpoint blockade." (PMID 32067413, 2020). "Furthermore, by up-regulating ARG-1, M2-TAMs also deplete the arginine pool for inducible nitric oxide synthase (iNOS), another enzyme that uses arginine to produce nitric oxide (NO), an important mediator of the immune responses against parasites and cancer." (PMID 33212945, 2020). "Increased ARG1 activity might lead to IDO1-dependent Trp starvation in cancer cells." (PMID 31354721, 2019). "The function of MDSC is highly depended on the cancer microenvironment and mediates its suppressive activity on the immune system through multiple mechanisms such as the production of ROS, nitric oxide (NO), and arginase (ARG-1) and secretion of the cytokines IL-10 and TGF-β1." (PMID 25436215, 2014). "In addition, STAT3 activation was reported to regulate ARG1 in MDSCs isolated from cancer patients." (PMID 25238263, 2014). "Therefore, ARG1 can be used as a specific marker for the frequency of granulocytic MDSC in cancers." (PMID 24741628, 2014). "Indeed, in a mouse model of human papillomavirus (HPV)-induced cancer, Arg1-expressing CD11b+F4/80+ macrophages infiltrated the tumors and inhibited T cell responses, including virus-specific T cells, by suppressing T cell proliferation and promoting a regulatory phenotype." (PMID 25250029, 2014). "Notably, exposure of macrophages to supernatant from ovarian (ID8) and breast (4T1) cancer cells promoted their re-education toward the protumoral CD206brightMHCII− phenotype, with CD206Bright cells being the most responsible for ARG1 production upon conditioning." (PMID 40588561, 2025). "Neutrophil-derived arginase 1 depletes microenvironmental arginine, inhibiting the CD3ζ signaling pathway and blocking CD8+ T cell activation, which aids cancer growth." (PMID 40626716, 2025). "Arginase (Arg1) is well-known for regulating cancer cell immune escape within the TME, and Fcer1g is a key gene involved in cancer immune infiltration." (PMID 40458726, 2025). "This is the case of arginine, which is converted into ornithine and urea by the enzymes arginase 1 (ARG1) and arginase 2 (ARG2), expressed by several cancer cells, as well as by MDSCs and TAMs." (PMID 41368640, 2025). "The production of urea cycle enzymes ARG1 and CPS1 was below detection levels in both cancers which is in accordance with the observations published by other authors." (PMID 40963742, 2025). "Cancer cell CM upregulated expression of M2 markers Mrc1 (CD206), Arg1 and Mgl2 in macrophages, but infection reduced it." (PMID 40547518, 2025). "Collectively, these data suggest the predominant role of Gαq/Calcium/PPAR-γ/Arg1 signaling as well as L-Arginine consumption in FFAR2 mediated immune suppression, which have great potential to be targets for cancer immunotherapy." (PMID 38402237, 2024). "In addition, we tested whether the gain-of-function of CCL20 in the Cat D KO cancer cells, CD204+ TAM polarization, and Cox2 and Arg1 expression were rescued in TAMs primed by CCL20 overexpression in the Cat D KO cancer cells compared with those of TAMs primed by the Cat D KO cancer cells." (PMID 38297161, 2024). "Consistent with previous studies, we confirmed that macrophages co-cultured with cancer cells exhibited high expression of CD163, CD206, Arg1, and IL-10, markers indicative of an M2 phenotype." (PMID 39877420, 2024).
cancer (continued). "The overexpression of ARG1 and ARG2 in cancer impairs T cell function involving L-arginine, which is necessary for T cell differentiation and proliferation." (PMID 39337272, 2024). "At the same time, lactic acid produced by cancer cells up-regulated VEGF and ARG1, promoting TAM differentiation into the M2 phenotype." (PMID 39192979, 2024). "When activated, MDSCs contribute to immunosuppression and cancer invasiveness through increased production of reactive nitrogen species (RNS), reactive oxygen species (ROS), and arginase 1 (ARG1) expression." (PMID 38533507, 2024). "MDSCs from patients with cancer express higher ARG‐1, IDO, IL10, and iNOS expression was higher in MDSCs from patients with cancer than from healthy donors." (PMID 37547175, 2023). "There is increased expression of key metabolic enzymes (Arg1, OAT and PYCR1) in fibrotic tissue and cancer." (PMID 37752116, 2023). "However, high amount of intratumoural ARG1+ neutrophils might not always be associated with worse cancer prognosis." (PMID 38007577, 2023). "For HCC model, markers including CK8, CK18, HepPar-1, Arg-1, AFP, HSP70, GPC3, CEA, CD24, CD133 and EpCAM can be used to identify cancer type and cancer progression." (PMID 37188191, 2023). "As cancer progresses, TAMs polarize into M2 macrophages via the upregulation of multiple markers, including CD163, CD206, PD-L1, and arginase 1 (ARG1)." (PMID 36831623, 2023). "T cells specific for such TMAs function, however, only in very immunocompromised microenvironments, which may explain why ARG1- or TGFβ-targeting therapeutic vaccines can activate specific immunity in animal models of cancer without causing associated side effects or systemic toxicity." (PMID 36175673, 2023). "In line with reported effects of arginine on glycolysis in cancers, we observed increased expression of glucose transporter 3 (GLUT3) and hexokinase 2 (HK2) in ARG1/AGMAT-expressing cells." (PMID 37804830, 2023). "Over-expression of ARG1 or ARG2 disrupts L-arginine homeostasis which leads to metabolic disorder-related diseases, Alzheimer’s disease (AD), cancer, etc." (PMID 36014374, 2022). "Macrophage migration inhibitory factor (MIF) secreted by CSCs inhibits anti-cancer immune responses via the CXCR2 pathway, increasing MDSC arginase-1 (ARG-1) expression and inhibiting CD8+T cell migration." (PMID 35269786, 2022). "The relevance of ARG1 and ARG2 in cancer, documented by many research groups, has prompted a search for pharmaceutical inhibitors of these enzymes in order to alter the outcome of the immune response and develop new treatment options." (PMID 36010962, 2022). "Arginase biology has been studied in multiple contexts, resulting in the identification of ARG1 and ARG2 as therapeutic targets in cancer, as well as potential biomarkers for cancer progression." (PMID 36010962, 2022). "Proteomic data showed that ARG1, ATP13A3, and SRM were highly expressed in cancer tissues, whereas PAOX and SMS had low expression." (PMID 36505496, 2022). "Previous studies have shown that Arg-1, GPC-3, and MUC1 can promote the proliferation and metastasis of malignant tumors and serve as prognostic biomarkers in several solid tumors." (PMID 34715880, 2021). "Thus, even if using the blockade of immune checkpoints could mask the inhibitory receptor activation of T cells, the hostile local immunosuppressive TME created by TAMs-derived factors (i.e., arginase-1 (Arg1) and interleukin-10) directly reduces the cytotoxicity of T cells against cancer cells." (PMID 33564072, 2021).
cancer (continued). "The recruitment of MDSCs usually occurs during inflammation and cancer and results in the elevation of some immunosuppressive factors, such as indoleamine 2,3 dioxygenase (IDO), arginase 1 (ARG-1), TGF-β, and reactive oxygen species (ROS)." (PMID 33728333, 2021). "Based on the reported immunosuppressive potential of MDSCs in malignant tumors, we analyzed the levels of key immunosuppressive mediators (IDO, ARG1, IL-6, and TGF-β1) in AEG patients." (PMID 33854974, 2021). "The results showed that most of the cells extracted from cancer tissue were HCC cells, and hepatocytes highly expressed CK-18, ALB, and ARG-1." (PMID 34776939, 2021). "During aerobic glycolysis, glucose is metabolized into lactate that is secreted by cancer cells, inducing VEGF and arginase 1 (ARG1) expression in TAMs." (PMID 34445193, 2021). "IL-6 activates an “M2” specific enzyme, Arginase-1 (ARG1), that can alter the extracellular matrix composition to drive cancer progression." (PMID 34566949, 2021). "And the expression of key enzymes CPS1, OTC, ARG1 in the urea cycle were lower than normal tissue in HCC and other cancers." (PMID 33869206, 2021). "High arginase levels, ARG1 or ARG2, are present in a variety of cancer types, including breast cancer, NSCLC, head and neck squamous cell cancer, kidney cancer, colorectal cancer, skin cancer, and cervical cancer." (PMID 32875727, 2020). "On the other hand, elevated arginase 1 (ARG1) produced mostly by MDSCs decreases l-arginine availability, thus decreasing the effector function in many cancers." (PMID 32823814, 2020). "The treatment of macrophages with medium harvested from MA-treated cancer cells in hypoxic condition showed a reduction of Arg1, CD206, YM1, and VEGF expression compared to the medium harvested from cancer cells in hypoxic condition." (PMID 31324019, 2019). "In contrast, Arg1, CD206, YM1, and VEGF expression was reduced in macrophages treated with medium harvested from MA-treated cancer cells in hypoxic condition." (PMID 31324019, 2019). "HIF-2α inactivation in ECs on the other hand led to decreased levels of arginase 1 (ARG1), which in turn increased the NO levels making the EC layer more accessible for cancer cells." (PMID 29896451, 2018). "ARG-1 (Arginase 1) produced by TAMs and MDSCs degrades arginine, while indoleamine 2,3-dioxygenase (IDO-1) produced by cancer cells, TAMs, and MDSCs converts tryptophane to an immunosuppressive metabolite kynurenine reducing T cell activity." (PMID 30158932, 2018). "The expression of Arg-1, IL-10, and VEGF in intratumoral macrophages in HSC-NOG-hIL-6 Tg mice suggests similarities with TAMs in cancer patients, and that they mediate immunosuppression in tumors." (PMID 29456539, 2018). "In our study, the cancer cells provoked M2 phenotype as demonstrated by an increase of CD163 and Arg1 and a decrease of IL-1b and IL-6 expression." (PMID 30180849, 2018). "Strong ex vivo responses against arginase peptide were detected in IFNγ ELISPOT and arginase-1 specific CD4+ and CD8+ memory T cells were found in both healthy donors and cancer patients." (PMID 30400835, 2018). "In cancer, Treatment of MDSC with COX inhibitors (COX2-i) have shown to down-regulate their production of ARG1 and iNOS, thereby reducing MDSC suppressive function." (PMID 30298121, 2018). "Keap-1 knocked-down amplified M2-macrophages induction by cancer cells, appearing as decreased IL-1b and IL-6 expression, and increased CD163 and Arg1 expression." (PMID 30180849, 2018). "In cancer patients, MDSCs isolated from different anatomical compartments were shown to have high levels of phosphorylated STAT3 that correlated with ARG1 expression, a downstream target of activated STAT3." (PMID 26700461, 2016). "ARG1 and NOS are expressed by MDSCs and ARG1 was found up-regulated also in plasma of cancer patients." (PMID 26700461, 2016).
cancer (continued). "Since immune suppression depends on the expression of ARG1 and IDO, these results open the possibility to combine specific inhibitors of these enzymes for the therapy of cancer." (PMID 26700461, 2016). "L-Arg depletion by myeloid-derived suppressor cells (MDSCs), which produce arginase 1 (ARG-1) and NO synthase 2 (NOS2), is observed in cancer patients." (PMID 27246354, 2016). "Cancer patients expressed higher mRNA levels of the M2 polarization markers CD163, ARG1 and IL-10 in CD11b+ cells and increased levels of the M2 cytokines IL-10 and CCL20 in plasma." (PMID 26840567, 2016). "In the present study, we showed the level of MDSCs in PBMC and Arg1 in plasma were significantly elevated in ECA patients, and the increased ratio of MDSC in PBMC was closely related to the expression of CD163 in cancer tissues." (PMID 25144454, 2014). "In addition, we analyzed the protein levels of IL6 and markers of TAMs, including matrix metalloproteinase 9 (MMP9) and arginase 1 (Arg1), in HCC cancer tissues and adjacent tissues." (PMID 39744421, 2025). "The most recent data on this topic have shown that MSLN can also drive macrophage polarization towards an immunosuppressive phenotype characterized by the secretion of VEGFA, ARG1, and S100A9, thereby stimulating cancer cell growth and weakening the immune response." (PMID 41335396, 2025). "Lactate, through HIF-1α, promotes M2 polarization of TAMs, upregulates vascular endothelial growth factor (VEGF) and arginase-1(ARG-1) expression; the former promotes angiogenesis while the latter catalyzes polyamine production to enhance cancer cell proliferation." (PMID 40028341, 2025). "MDSCs can inhibit Teffs by releasing arginase 1 (Arg1), nitric oxide synthase 2 (NOS2), reactive oxygen species (ROS), cyclooxygenase 2 (COX2), TGF-β, etc., thereby promoting the progression of various cancers." (PMID 40008144, 2025). "In a TME characterized by low glucose levels, TAMs modulate their functions through glycolysis activation, while lactate promotes the polarization of M2-type TAMs, leading to elevated expression of VEGF and arginase-1 (ARG-1) and thereby stimulating cancer cell proliferation." (PMID 39925801, 2025). "Lower expression of Cox2 and Arg1 and reduced CD204+ polarization were observed in the THP-1 cells cultured with CM from the CCL20 siRNA-transfected cancer cells compared with those from the cells cultured with CM from the cont siRNA-transfected cancer cells." (PMID 38297161, 2024). "The two arginase isoforms, arginase 1 (ARG1) and arginase 2 (ARG2), regulate the proliferation of cancer cells, migration, and apoptosis; affect immunosuppression; and promote the synthesis of polyamines, leading to the development of cancer." (PMID 39337272, 2024). "Given that increased ARG1-expressing TAMs were seen in FIH MKO mice, we hypothesized that signals secreted from cancer cells, such as LLC cells, may influence Arg1 expression in an FIH-dependent way." (PMID 38422022, 2024). "In these hemorrhagic regions, we found an increased Cd68 signal, confirming macrophage infiltration, superimposed by upregulated expression of Hmox1 and Arg1, the latter of which is the archetypal marker for procancerous and immunosuppressive TAMs in mice, similar to CD163 and SPP1 in human cancers." (PMID 38060331, 2023). "This correlation between ARG1/AGMAT status and expression of the signature genes further supports the hypothesis that ARG1/AGMAT-controlled arginine levels determine cancer metabolism." (PMID 37804830, 2023). "Taken together, LTF, ARG1, PGLYRP1, S100A12 and CAMP/LL-37 affect the human immune system at various levels by producing both protumorigenic and anticancer effects in a tissue- and cancer-specific manner." (PMID 36230605, 2022). "Arg-1 (and other soluble mediators) synthesized by MDSC is locally suppressive of T cells, these processes accounting at least partially for the higher NLR seen across the common cancers." (PMID 36230888, 2022).